L1CAM (L1 cell adhesion molecule)
Diseases named in the same sentence as L1CAM in open-access papers (continued):
Sharing a sentence is not in itself a finding about the gene and the disease.
tumor (continued). "The NSMP group may further be stratified based on histological (i.e., tumor grade and histotype, LVSI, depth of myometrial invasion), immunohistochemical (i.e., L1CAM expression), or molecular (i.e., CTNNB1 mutation) features." (PMID 35463299, 2022). "Since high L1CAM expression characterizes platinum resistant disease, there is a rationale in combining L1CAM MAbs with chemotherapy because L1CAM inactivation may re‐sensitize tumour cells to standard chemotherapy." (PMID 35429348, 2022). "In addition, L1CAM knockdown results in reduced tumorigenicity and decreases viability and tumor growth of etoposide‐resistant RB cell lines." (PMID 34228897, 2022). "In addition, the L1CAM in the tumor cell surface or the shedding L1CAM cleaved from the tumor cell surface into blood can exert their biological function mainly through binding to themselves (homophilic) or other partners such as integrins (heterophilic)." (PMID 36387224, 2022). "However, the detailed mechanism of how Integrin β1 and L1CAM regulate tumor chemoresistance needs further study." (PMID 35517416, 2022). "By enriching the clinical variables with biomarker information, namely estrogen receptor and L1 cell adhesion molecule expression status indicators, peritoneal washing status and tumor size < 5 cm, we improve the discrimination and calibration performance of the CPH and OST models." (PMID 36513790, 2022). "After depletion of L1CAM in etoposide‐resistant RB tumor cells followed by retreatment with etoposide, we could show that all cell lines investigated exhibited decreased viability in vitro." (PMID 34228897, 2022). "In the HEC-1A cells line, L1CAM could promote the upgrowth of tumor initiating cells to accelerate epithelial mesenchymal transformation (EMT), thereby facilitating the resistance of anoikis and affecting the tumor progression of GC patients." (PMID 36713571, 2022). "Positive L1CAM expressions in the metastatic brain lesions were accompanied with significantly increased peripheral platelet counts in patients treated with neurosurgical tumor resection (P < 0.05)." (PMID 36387224, 2022). "The benefit of radiotherapy was also observed in patients with endometrioid L1CAM positive tumours." (PMID 34659530, 2021). "We compared trafficking, expansion and tumor control for T cells expressing different CAR construct designs targeting two antigens (L1CAM or HER2), structurally identical except for spacer (long or short) or co-stimulatory (4-1BB or CD28) domains to be evaluated." (PMID 33801448, 2021). "We found that the expression of FOXP3 and CCR4, and the percentage of CD4+FOXP3+ and FOXP3+CCR4+ Tregs chemoattracted to the tumor sites were significantly downregulated in the shL1CAM group, but upregulated in the L1CAM overexpression group, as compared with the control." (PMID 33710805, 2021). "We thus speculate that a triple combination of 5-FU + SB43152 and a CXCR4 inhibitor (e.g., AMD070) or L1CAM inhibitor could be an effective therapeutic strategy to eradicate the tumor." (PMID 33897875, 2021). "Although the authors observed different L1CAM serum levels in EC patients compared to individuals with benign gynecological conditions, they were unable to demonstrate correlation among L1CAM serum levels and stage, histological type or tumor grading." (PMID 34203959, 2021). "We microscopically investigated whether we see L1CAM-CAR T cells within the bioprinted 3D tumor models." (PMID 34267756, 2021). "However, patients with L1CAM positive tumours showed improved disease-specific survival if treated with adjuvant radiotherapy." (PMID 34659530, 2021). "An important corollary to this paradigm is that combining L1CAM-targeted treatments with conventional chemotherapy may eradicate OC by hitting the residual population of tumor-initiating and drug-resistant OCSC." (PMID 34645505, 2021).
tumor (continued). "Furthermore, our study cohort is heterogeneous and has relatively few patients, which limited our power to study the prognostic significance of L1CAM in specific subgroups of tumour." (PMID 34659530, 2021). "The co-localization of L1CAM and pSTAT3 was also detected in several tumor vessels, in accordance with our previous demonstration of a functional cross-talk between the two molecules in tumor endothelium." (PMID 34645505, 2021). "L1CAM was associated with high-risk features such as non-endometrioid histology, high tumour grade, and high FIGO stage." (PMID 34659530, 2021). "PD-L1 was positive in 21 (43.75%) tumor samples, while L1CAM was positive in 25 (52.08%) samples." (PMID 33387039, 2021). "To further address whether TGF-β might be implicated in Treg-enhanced L1CAM expression, we included a TGF-β inhibitor in the Treg and tumor cell co-culture assay." (PMID 33710805, 2021). "The inhibition of STAT3 prevented L1CAM-dependent OC stemness and tumor initiation." (PMID 34645505, 2021). "Besides radioimmunotherapy, the conjugation of L1CAM antibodies with various radioisotopes has generated reagents that found interesting applications in tumor imaging." (PMID 32429448, 2020). "L1CAM expression was evaluated in the tumour epithelial compartment." (PMID 32291413, 2020). "Because the specificity of L1CM is relatively low, we hope that L1CAM could be used as a potential biomarker to combine with some established tumor markers (such as CEA, CA724, CA19-9, CA242) for the diagnosis of GC and EJA." (PMID 32742486, 2020). "This might open a novel scenario whereby L1CAM could also orchestrate stemness in the tumor microenvironment, adding a further layer of complexity to its role in cancer progression." (PMID 32429448, 2020). "L1CAM is overexpressed in various types of human cancers, including ovarian and endometrial carcinoma, colon cancer, melanoma and glioblastoma, and it usually correlates with advanced tumor stage and poor prognosis." (PMID 32257947, 2020). "Indeed, L1CAM-targeted therapies resulted in multiple advantages, among which are counteracting tumor cell invasion, EMT and metastasis initiation, and pro-malignant interactions between tumor cells and their microenvironment." (PMID 32429448, 2020). "L1CAM promoted the establishment of a microenvironment that could favor immune escape and might contribute to tumor progression and chemoresistance." (PMID 32429448, 2020). "In addition, it would be helpful to identify new CSC cell surface markers that are not expressed in normal stem cells but are also present in the bulk population of tumor cells, like L1CAM in ovarian CSCs." (PMID 32257947, 2020). "Numerous studies focused on the function of L1CAM in tumor-related processes." (PMID 32429448, 2020). "Therefore, loss of the putative tumour suppressor L1CAM increases the CSC population and/or features, suggesting that L1CAM promotes epithelial (cancer) cell differentiation." (PMID 32291413, 2020). "Furthermore, emerging evidence (mentioned in Section 5.1) also points to a crosstalk of L1CAM with the tumor immune microenvironment which contributes to immune evasion." (PMID 32429448, 2020). "This systematic review selected for studies in which the mechanisms of L1CAM in tumor progression were addressed, and if possible, could be linked to a specific domain of L1CAM." (PMID 31455004, 2019). "L1CAM was demonstrated to be involved in different pro-tumor events such as metastasis, epithelial-to-mesenchymal transition (EMT), and is associated with aggressive tumor phenotypes, and chemoresistance." (PMID 31455004, 2019).
tumor (continued). "Thus, results from clinical analyses should be considered in the context of the tumor microenvironment and along with activation of other pathways, such as activation of integrins, growth factor receptors, and L1CAM-intrinsic pathways." (PMID 31455004, 2019). "In this case, it may become necessary to discriminate between vessel-derived L1-ΔTM and the ectodomain of transmembrane L1CAM which is released by various cell types, including tumor cells, upon proteolytic cleavage." (PMID 30829570, 2019). "L1 cell adhesion molecule (L1CAM) is highly expressed in malignant tumours and might play a pivotal role in tumour progression." (PMID 31754264, 2019). "Besides the prognostic value of L1CAM, the protein is considered to be suitable for targeted therapy because of its role in tumor progression." (PMID 31455004, 2019). "In addition to its role in neurogenesis, L1CAM is involved in tumor progression of multiple cancers." (PMID 31455004, 2019). "Indeed, in most cases only a fraction of vessels within tumor and inflammatory tissues (i.e. the most prominent conditions where vascular L1CAM is detected), exhibits L1CAM expression." (PMID 30829570, 2019). "Specifically, it must be kept in mind that cell-associated L1CAM staining, as observed in IHC, or increased L1CAM transcription, as assayed by mRNA analyses, does not necessarily directly reflect L1CAM-induced tumor-promoting signaling in the same cell." (PMID 31455004, 2019). "Senescent cells represent premalignant cellular forms, and the expression of the L1CAM oncoprotein in senescent cells may provide them with specific features that can be inherited by tumor cells bypassing the senescence state." (PMID 29615539, 2018). "L1CAM “is a major driver for tumour cell invasion and motility”." (PMID 30253737, 2018). "The role of L1CAM in tumor cells is to maintain tumor growth, metastasis, and angiogenesis." (PMID 30116755, 2018). "Based on the correlation between the L1CAM level and tumor invasiveness it cannot be excluded that migration of senescent cells in the tissues might also be affected by L1CAM expression." (PMID 29615539, 2018). "Taken together, both Mint3 and L1CAM in CAFs promoted cancer cell proliferation and tumour growth." (PMID 28504692, 2017). "Finally, the genetic manipulation of endothelial L1CAM in the context of a mouse tumor model revealed that L1CAM in tumor vessels prevents their morphological and functional maturation." (PMID 28134764, 2017). "Representative tumor sections were stained for SerpinB2, Neuroserpin, and L1CAM." (PMID 29207598, 2017). "Additionally, three large studies have demonstrated that L1 cell adhesion molecule (L1CAM; CD171) expression in more than 10% of tumour cells is a strong independent predictor for distant recurrences in EC." (PMID 28424422, 2017). "We further examined whether L1CAM expression in Mint3 KO MEFs restores tumour growth of co-injected cancer cells." (PMID 28504692, 2017). "In addition, increased expression of L1CAM enhances proliferation, migration, invasion, and/or cisplatin resistance of ICC and GBC cells and tumor growth in vivo, while down-regulation of L1CAM reduces them." (PMID 28166242, 2017). "The different signaling mechanisms could translate into the activation of different kinases that phosphorylate L1CAM and thereby play different role in different tumor stage." (PMID 28428626, 2017). "Endothelial expression of L1CAM appears to be under the control of angiogenic and inflammatory cytokines that are abundantly released in the tumor microenvironment, including VEGF-A, angiopoietin-like 4, tumor necrosis factor-α, interferon-γ, and transforming growth factor β1." (PMID 28134764, 2017).
tumor (continued). "Transcriptomic profile analysis showed that two genes (L1CAM and FBN1) were upregulated and that four genes (AUST2, MAPT, AGT and USH1C) and two microRNAs (hsa-mir-100 and hsa-mir-378) were downregulated, all of which were associated with tumor malignancy." (PMID 29215599, 2017). "In addition, L1CAM expression has been identified in a variety of tumor types and correlates with poor prognosis and metastasis." (PMID 28166242, 2017). "To investigate whether inhibition of tumor cell proliferation by Ab417 was due to decreased membrane L1CAM level, we performed an antibody internalization assay using SCK-L1 cells." (PMID 28166242, 2017). "This again might reflect the L1CAM participation in tumor progression and its re-expression and cleavage in the more advanced stages." (PMID 27832351, 2017). "In cases 4 and 5, more than 10% L1CAM expression was observed in two out of three tumour blocks." (PMID 28424422, 2017). "Subsequently, L1CAM-depleted (shL1CAM) CAFs were prepared to examine whether L1CAM in CAFs is also involved in tumour growth." (PMID 28504692, 2017). "Indeed, ablating L1CAM from the tumor vasculature restored endothelial polarity, basement membrane deposition, and pericyte coverage." (PMID 28134764, 2017). "It would be of interest to elucidate whether L1CAM inhibition-mediated normalization improves tumor perfusion and, hence, delivery of cytotoxic drugs or other anticancer therapeutics." (PMID 28134764, 2017). "Next, we investigated whether Mint3 in human CAFs also controls L1CAM expression and tumour growth as observed in MEFs." (PMID 28504692, 2017). "In carcinoma cell lines, L1CAM-expression augments cell motility and tumor growth." (PMID 26891628, 2016). "A small percentage of these cases showed areas of non-endometrioid differentiation in less than 10 % of the tumor, and this was associated with L1CAM-expression." (PMID 26891628, 2016). "As L1-CAM is known to be expressed on several normal tissues including the stomach, kidney, adrenal glands, and in certain regions of the nervous system, these future studies are also warranted to address potential on-target off-tumor toxicity of L1-CAM-specific CAR T cells." (PMID 26761817, 2016). "Therefore our work contributes to the growing evidence showing efficacy of inhibiting tumour growth by L1CAM antibodies and stresses the need for further evaluating its therapeutic potential in vulvar and other cancers." (PMID 27028855, 2016). "If L1CAM-expression is present in EECs, it is associated with poor tumor differentiation, absence of estrogen- and progesterone receptors, and loss of E-cadherin expression." (PMID 26891628, 2016). "Furthermore, a significant positive correlation between the level of L1CAM and the grade of tumor differentiation (p=0.04), the FIGO stage (p=0.025) as well as the histological subtype (p= 0.002) was found." (PMID 27174921, 2016). "In addition, L1CAM-staining was observed to be strongest at the invasive front, which confirms the suggestion that L1CAM is important for tumor invasion." (PMID 26891628, 2016). "Further work is needed to understand the effect of L1CAM on proliferation, however, other reports point towards a link to the Erk1/2 and the Akt-pathways, which both are known to accelerate proliferation and growth of tumor cells." (PMID 25860483, 2015). "During this time, a reduced tumour burden with a significant decrease in average RTV on day 13 was observable for mice treated with anti-L1CAM combination therapy compared to all other treatment groups (vs. 177Lu-DOTA-chCE7: p < 0.05; vs. PTX: p < 0.05; vs. 177Lu-DOTA-control IgG + PTX: p < 0.05)." (PMID 26116117, 2014). "The expression of L1CAM in tumor cells can be enhanced by various means." (PMID 24497324, 2014).
tumor (continued). "When tumor cells enter the circulation, the L1CAM expressed on the cell surface may allow cancer cells to aggregate and survive in blood stream and growth at distant metastatic sites through cell-cell and/or cell-ECM contact." (PMID 25294816, 2014). "Thus, due to its ability to trigger essential cancer-related processes, L1CAM is considered as driver of tumor progression." (PMID 25510351, 2014). "However, L1CAM has recently been shown to be expressed in human tumors and correlate with tumor progression, poor prognosis and the advanced stages of cancer." (PMID 24660028, 2014). "An effective treatment against L1CAM-positive tumour cells in the peritoneal cavity might therefore decrease the amount of free tumour cells (spheroids) potentially reducing the burden of occurring ascites." (PMID 26116117, 2014). "L1CAM can profoundly affect cell migration and invasion of tumor cells." (PMID 24497324, 2014). "In contrast to L1CAM, the role of tumor-related FoxP3 expression in PDAC development is less known." (PMID 24797069, 2014). "Primary EC tumor tissues showed a variable methylation pattern of the L1CAM promoter." (PMID 23530769, 2013). "L1CAM protein was detected in 23.9% of human non-tumor mucosa samples." (PMID 24422715, 2013). "Recent studies demonstrated L1CAM expression in various types of cancer, predominantly at the invasive front of tumors and in metastases, which indicates its involvement in advanced stages of tumor progression." (PMID 24422715, 2013). "L1cam protein was mainly located in the cytoplasm and cell membrane of tumor cells." (PMID 23806079, 2013). "Expression of L1CAM correlated with age, tumor location, size of tumors, Lauren’s classification, depth of invasion, lymph node and distant metastases, regional lymph node stage, Tumor-Node-Metastasis (TNM) stage and prognosis." (PMID 24422715, 2013). "SSEA-5 and L1CAM displayed immunoreactivity in different subsets of tumor cell lines." (PMID 26317026, 2013). "Whether Galβ1–4Galβ1- is located specifically on L1CAM glycoprotein or on glycoproteins of other tumours and cancer is another question to answer." (PMID 22544341, 2013). "L1CAM has been defined as a key driver for tumor cell invasion and EMT." (PMID 23819113, 2013). "L1CAM immunostaining was mainly localized on the membrane of tumor cells of HCC tissues." (PMID 22888955, 2012). "Then, the expression of L1CAM in HCC tissues with advanced tumor stage and grade was significantly higher than that in early tumor stage and low tumor grade HCC, suggesting that L1CAM expression might be of clinical relevance in the aggressiveness of HCC." (PMID 22888955, 2012). "Additionally, they suggested that L1CAM expression in HCC was significantly correlated with the advanced tumor progression and was an independent poor prognostic factor for both overall survival and disease-free survival in patients with HCC." (PMID 23111165, 2012). "Cell adhesion molecules such as CD44 or L1-CAM may be involved in the migration of tumor cells and the cleavage events are required for L1- or CD44-dependent cell migration." (PMID 23251384, 2012). "Taken together, we characterized FL-L1CAM and not the so-called tumour-associated splice variant as the metastasis-promoting isoform of L1CAM." (PMID 21541352, 2011). "In a previous study, L1CAM has been shown to promote invasion of tumour cells." (PMID 21541352, 2011). "This raises the important question how L1CAM expression is regulated in human tumours." (PMID 20799950, 2010). "Thus, our results obtained in human tumour cell lines recapitulate the findings in neural cells and demonstrate that the human L1CAM gene has two active promoter elements that are differentially used." (PMID 20799950, 2010). "Our results provide the basis for a better understanding of L1CAM regulation in tumours." (PMID 20799950, 2010).